TNF (tumor necrosis factor)
Diseases named in the same sentence as TNF in open-access papers (continued):
Sharing a sentence is not in itself a finding about the gene and the disease.
Sepsis (continued). "Serum levels of MMP-9, MMP-10, TIMP-1, tumor necrosis factor (TNF)-alpha, and interleukin (IL)-10 were measured in patients with severe sepsis at the time of diagnosis and in healthy controls." (PMID 19799791, 2009). "Release of both TNFα and IL-6 from monocytes was lower in patients with VAP-related sepsis than with sepsis related to other types of infection." (PMID 19883512, 2009). "TNF-α and IL-6 were estimated in 30 elderly patients admitted to our intensive care unit with SIRS and sepsis." (PMID 19881187, 2009). "Previous studies of our group showed that induction of sepsis by cecal ligation and puncture (CLP) leads to a significant increase in the plasma levels of TNF-α, IL-6, and IL-10." (PMID 19594900, 2009). "TNFα and IL-6 production from LPS-stimulated monocytes was lower in patients with VAP-related sepsis than with sepsis due to other infections." (PMID 19883512, 2009). "TNF-α, MIP-1α, MCP-1, and IFN-γ have been measured in patients with sepsis and acute respiratory distress syndrome and are correlated with poor outcomes." (PMID 18937852, 2008). "Despite the remarkable success in preclinical models, most anti-inflammatory therapies targeting cytokine storms (such as anti-TNF-α, anti-IL-1β, and anti-endotoxin agents) have failed to significantly reduce mortality in large Phase 3 sepsis clinical trials." (PMID 41521316, 2026). "Also, TNF-α is believed to be directly involved in progression of S-AKI, since its levels correlate with sepsis intensity." (PMID 41614949, 2026). "The stored blood samples were estimated for TNF-α, A Disintegrin and Metalloproteinase Motifs 13 (ADAMTS13), and soluble Fas ligand (FasL) at the end of the study to confirm the biomarker-based inflammatory phenotypes of sepsis-induced MOFS." (PMID 41883885, 2026). "Consistent with our in vivo sepsis lung tissue data, Fer-1 significantly attenuated LPS induced expression of proinflammatory cytokines IL-1β and IL-6, but not TNFα, as well as the chemokine CXCL1 and chemokine receptor CCR5." (PMID 41518848, 2026). "We plan to validate the efficacy of these drugs in sepsis mouse models, such as those induced by intraperitoneal injection of LPS or cecal ligation and puncture (CLP), observing their impact on inflammatory cytokines (e.g., TNF-α and IL-6) and survival rates." (PMID 40124361, 2025). "Mechanistically, microbial translocation in sepsis results in the activation of hepatic Kupffer cells through TLR4 signaling, which triggers downstream NF-κB activation and induces the release of proinflammatory cytokines such as TNF-α and IL-1β." (PMID 41268545, 2025). "The identification of TNF and IL1B as bridging proteins between systemic inflammation and neurological processes, combined with respiratory-centric disease enrichment patterns, provides mechanistic insights into sepsis pathophysiology." (PMID 41299255, 2025). "LPS increases the activity of HDAC3 through mitochondrial reactive oxygen species and c‐Src signalling, inhibits the accumulation of NF‐κB/p65 at the TNF‐α promoter and promotes the expression of TNF‐α, which is involved in the pathogenesis of sepsis‐induced myocardial injury." (PMID 40497340, 2025). "One study investigated the effect of the β1-AR antagonist esmolol on sepsis with the preclinical CLP model in rats, revealing that esmolol improved survival, reduced intraperitoneal TNF-α concentrations and E. coli translocation to draining lymph nodes, and prevented damage to the gut mucosa." (PMID 41124072, 2025). "In this study, we revealed that T0 protects against sepsis-related ALI via the following mechanisms: the total protein in the BALF was decreased; TNFα and IL6 mRNA expression levels were decreased in animals and cells; H&E staining revealed that the degree of lung injury was improved." (PMID 40994643, 2025).
Sepsis (continued). "Several studies have demonstrated that aptamer-based biosensors match or exceed antibody-based systems in sensitivity, often reaching femtomolar or even attomolar detection limits for sepsis-related biomarkers, such as IL-6, CRP, and tumor necrosis factor-alpha (TNF-α)." (PMID 40710052, 2025). "Moreover, it reduced circulating levels of cytokines IL-1β, IL-6, TNF-α, IL-10, and MCP-1 in a mouse model of cecal-ligation-and-puncture-induced sepsis." (PMID 40473887, 2025). "Furthermore, the MIF inhibitor also mitigated the effects of CSN6 on the mRNA expression levels of pro-inflammatory cytokines IL-1β, IL-6, TNF-α, and collagen I/III in macrophages in an in vitro sepsis model (n = 6 per group)." (PMID 40595050, 2025). "In sepsis, FMR1 expression has been associated with altered immune cell function and inflammatory responses; moreover, the absence of FMRP induces TNF-mediated apoptosis and necroptosis in infections and liver diseases." (PMID 40861493, 2025). "The protein expression levels of four upregulated necroptosis‐related DEGs (PYGL, TNF‐α, CYLD and FADD) were significantly higher in the sepsis group than in the control group in all three cells, whereas the TLR3 level was only significantly higher in HUVEC cells." (PMID 40318009, 2025). "At the same time, during the development of sepsis, the expressions of JAK2 and STAT3 proteins were significantly up-regulated, and the transcription and expression of downstream inflammatory factors IL-6 and TNF-α were also increased." (PMID 40338919, 2025). "However, ACE also drives pro-inflammatory signaling via Ang II–AT1R activation, inducing cytokine release (TNF-α, IL-6, IFN-γ) and ROS production, potentially exacerbating inflammation in sepsis or viral infections." (PMID 40722848, 2025). "Secondly, as this is a retrospective study, the expressions of important inflammatory cytokines in sepsis such as interleukin, tumor necrosis factor and interferon were not tested at that time for some patients, so we excluded these variables." (PMID 40290256, 2025). "Similarly, under the influence of sepsis-induced inflammation, senescent cells release SASP factors such as IL-6 and TNF-α." (PMID 40299574, 2025). "Panax ginseng and its active ginsenosides (e.g., Rg1) have been shown to alleviate intestinal barrier disruption and suppress pro-inflammatory cytokines in CLP-induced sepsis, potentially through inhibition of the TLR4/NF-κB pathway, leading to reduced IL-6 and TNF-α levels." (PMID 41357500, 2025). "In this study, we found that the TNF-α level of the SAE group was significantly higher than that of the non-SAE sepsis group." (PMID 40529149, 2025). "TNF-α levels were significantly elevated in the sepsis and all TCZ-treated groups compared to the healthy group, with a lower increase in the TCZ1 group than in the sepsis and TCZ treatment groups." (PMID 39955435, 2025). "Many of the immunological markers discussed in this review, such as interleukin-6 (IL-6), tumor necrosis factor-alpha (TNF-α), interleukin-1 beta (IL-1β), and myeloperoxidase (MPO), have been extensively studied in the contexts of sepsis, cardiovascular disease, or general critical illness." (PMID 40710793, 2025). "The study of Wei Zhou suggest XBJI may modulating the IL-17, TNF, NF-κB, and TLR pathways, and targeting IL-1β, IL-6, and TNF, thereby exert therapeutic effects on sepsis." (PMID 40308770, 2025). "This study aimed to investigate the effects of cetirizine and dexamethasone (alone and in combination) on serum levels of Maresin-1 (MaR-1), TNF-α, IFN-γ, IL-1, IL-2, IL-6, IL-8, and IL-10 in a rat model of sepsis induced by the cecal ligation and puncture (CLP) method." (PMID 41517447, 2025). "It suppresses the expression of TNF-α, IL-6, and malondialdehyde in serum and tissues, and augments the levels of SOD and GSH to counteract sepsis-related damage induced by abdominal puncture-induced sepsis, thereby preserving intestinal mucosal barrier function." (PMID 40258745, 2025).
Sepsis (continued). "The cytokine storm in sepsis is multi-faceted and timing-dependent; bluntly blocking one mediator (e.g., TNF) without patient stratification has not reduced overall mortality." (PMID 41009426, 2025). "In addition, several markers, including Calprotectin, Azurocidin, IL-6, IL-8, IL-10, TNF-α, and IL-35, were progressively elevated from SIRS to Sepsis_A and Sepsis_D cohorts, reflecting disease severity." (PMID 41301767, 2025). "Therefore, this study aimed to investigate the effects of cetirizine and dexamethasone (alone and in combination) on serum levels of MaR-1, TNF-α, IFN-γ, IL-1, IL-2, IL-6, IL-8, and IL-10 in a rat model of sepsis induced by CLP method." (PMID 41517447, 2025). "Sepsis can also induce severe oxidative stress in the kidneys, as evidenced by elevated levels of MDA, a key end product of lipid peroxidation, and is accompanied by marked upregulation of inflammatory cytokines including IL-1β and TNF-α." (PMID 40993513, 2025). "A systematic review and meta-analysis has shown that mean concentration of TNF-α in septic patients is elevated nearly 10-fold compared to healthy individuals, and TNF-α is associated with sepsis mortality, but not sepsis severity." (PMID 41042728, 2025). "At the 4th hour following CLP-induced sepsis, levels of NEU, IL-1, and TNF-α increased markedly." (PMID 41517447, 2025). "In parallel, the administration of butyrate, but not acetate, partly attenuated sepsis severity (gut permeability and serum TNF-α)." (PMID 41444762, 2025). "While plasma inflammatory cytokine levels also rise during endotoxemia, such as sepsis, it has been reported that TNF-α and IL-1β do not increase in response to exercise-induced cytokine production, a pattern similarly observed in this study." (PMID 41154623, 2025). "Tα1 inhibits the expressions of TNF-α and IL-6 in sepsis rats and weakens the activity of the Notch signaling pathway, thereby preventing the progression of inflammation and alleviating sepsis-induced lung injury." (PMID 40599771, 2025). "Assays of plasma showed significantly lower levels of interferon-γ and TNF-α in heatstroke patients than in patients with cardiopulmonary bypass but not in patients with sepsis, consistent with T cell exhaustion." (PMID 40084252, 2025). "In sepsis, SIRT1 accumulates at IL‐1β/TNF‐α promoters with NAD+‐enhanced H3K16 deacetylation." (PMID 41208649, 2025). "Moreover, taurine can diminish levels of inflammatory factors like interleukin-1β (IL-1β) and tumor necrosis factor-α (TNF-α) in lung tissue by suppressing the p38/MAPK and NF-κB signaling pathways, thereby attenuating sepsis-induced lung injury." (PMID 41380328, 2025). "Additionally, SHARPIN has other physiological roles in various processes, such as tumor necrosis factor-α (TNF-α)-induced cell death, regulation of caspase 1 activity in sepsis, and the progression of many types of cancers." (PMID 38351238, 2024). "Berberine-mediated blockade of HMGB1/receptor for advanced glycation end products signaling reduces the expression of TNF-α, IL-1α, and complement C1q A chain in the hippocampus of CLP mice, inhibits the activation of microglia, and thus alleviates sepsis-induced cognitive impairment." (PMID 38734709, 2024). "The NORASEPT II study, as reported in The Lancet in 1998, and a 1995 JAMA study explored the potential of an anti-TNF-α monoclonal antibody (TNF-α MAb) for treating sepsis and septic shock, yielding critical insights into the challenges of targeting TNF-α in sepsis therapy." (PMID 39056754, 2024). "Using cytokine injections and perturbations in vivo, we discovered a hierarchical cytokine module composed of TNF, IL-18, IFN-γ and IL-1β that sufficed to explain most of the organism-wide response to sepsis, ranging from genes to cells to tissue physiology and host fitness." (PMID 38191855, 2024).
Sepsis (continued). "An amount of production of pro-inflammatory cytokines such as TNF-α, IL-1β, and IL-8 are relevant to tissue injuries, sepsis, and noninfectious systemic inflammatory response syndrome in dogs." (PMID 38535325, 2024). "Unfortunately, the earliest clinical trials for treating sepsis with TNF‐specific antibodies did not yield the anticipated results." (PMID 39660881, 2024). "Additionally, the expression of IL1β, TNFα, and IL6 in BALF from FGF2 KO mice was higher than that in WT mice in the sepsis model." (PMID 39436561, 2024). "Sepsis diagnosis is based on the presence of certain biomarkers in the patient’s blood, for instance, C-reactive protein (CRP), procalcitonin (PCT), tumor necrosis factor-alpha (TNF-α), high-mobility group box 1 protein (HMGB-1), and interleukin-6 (IL-6)." (PMID 38920613, 2024). "Of note, IL-1b, IL-6, IL-10, TNF-a, and suPAR did not significantly change during the first week of sepsis (p > 0.05)." (PMID 39272772, 2024). "Besides that, TNF-α has been considered as a potential differentiating biomarker between FMF and sepsis when its levels were co-determined with granulocyte-monocyte colony-stimulating factor (GM-CSF)." (PMID 39132307, 2024). "However, drugs targeting inflammatory mediators, like IL-1β, TNF-α, or TLR, to suppress inflammation are ineffective in improving survival in sepsis patients." (PMID 38558800, 2024). "Pediatric burn patients with sepsis exhibit elevated serum levels of TNF-α and IL-6 as compared to their non-septic counterparts." (PMID 39716257, 2024). "In contrast to our observations, prior research has reported that thymoquinone (10 mg/kg, 10 days, PO) reduced TNF-α levels in rats with ischemia-reperfusion injury and that thymoquinone (50 mg/kg, 2 weeks, PO) decreased TNF-α levels in mice with sepsis-induced AKI." (PMID 38629092, 2024). "The measurement of TNF-α and IL-6 levels in lung tissue by ELISA revealed that BRD3308 mitigated the release of inflammatory cytokines, which indicated that BRD3308 had a significant anti-inflammatory effect on sepsis-induced ALI." (PMID 39224841, 2024). "Moreover, when evaluated in vivo on mice sepsis model, both nanosystems have demonstrated a superior effect over the uncoated AMPNP regarding the reduction in serum cytokines (IL-1β, TNF-α, and IL-6) levels and inflammatory cells tissue infiltration." (PMID 38637839, 2024). "We observed that resveratrol, both in its native form and encapsulated within silver nanoparticles, could substantially mitigate the sepsis-induced changes in the expression of Bcl-2, Caspase-3, TLR4, IL-1Β, and TNF-α." (PMID 38546748, 2024). "Furthermore, the baseline excessive pro-inflammatory cytokines, such as TNF-α, IL-6, IL-1α, IL-1β, and IL-18, released after hepatic cell damage in NASH or further stage, might predispose NAFLD patients to cytokine storm in the setting of sepsis, resulting in worse outcomes." (PMID 39407795, 2024). "Tumor Necrosis Factor-alpha (TNF-α) is a key proinflammatory cytokine involved in systemic inflammation, playing a role in inducing fever, shock, tissue injury, and, in severe cases, sepsis." (PMID 39589620, 2024). "Contrary to the expression patterns observed for anti-apoptotic markers, we found that pro-apoptotic and pro-inflammatory markers Caspase-3, P2X7R, TLR4, IL-1Β, and TNF-α saw a considerable surge in the CLP group, a reflection of the pronounced inflammatory response instigated by sepsis." (PMID 38546748, 2024). "Compared with wild-type mice in CLP sepsis models, mice with FXI knockout had smaller increases in the plasma levels of inflammatory cytokines TNF-α and interleukin-10 (IL-10), delayed responses to the inflammatory cytokines IL-1β and IL-6, and a greater survival advantage." (PMID 38213768, 2024).
Sepsis (continued). "This review links molecules (TNF-α, CCL2, ROS, VEGF, MMP-9, and NO) secreted by macrophages under inflammatory conditions to endothelial cell dysfunction (adhesion, permeability, and coagulability), refining the pathophysiologic mechanisms of sepsis." (PMID 39199368, 2024). "However, recent studies have demonstrated that deficiency of RIPK3 or gasdermin D (GSDMD) can protect against TNF-induced SIRS, CLP-induced sepsis, or lipopolysaccharide (LPS)-induced septic shock." (PMID 38684668, 2024). "There were no statistically significant variations in serum TNF-α levels between the vehicle and sepsis groups or between the normal and sham groups." (PMID 39144689, 2024). "In addition, quercetin has been shown to mitigate sepsis-induced ARDS, as it blocks the effects of NOD-like receptors, NF-κB, TNF, and HIF-1, thus reducing overall oxidative stress, inflammation, and tissue damage." (PMID 39126050, 2024). "Another study investigated the role of FGD5-AS1 in sepsis and LPS-induced inflammation and showed that FGD5-AS1 overexpression increased AQP1 and decreased miR-133a-3p expression, subsequently reducing inflammatory cytokines such as TNF-α, IL-6 and IL-1β." (PMID 39544938, 2024). "Since TNF-α orchestrates numerous pathologic effects observed in septic shock, it is suggested that sustained macrophage survival mediated by TNF-α is essential in sepsis." (PMID 39134731, 2024). "Although in animal sepsis models, the use of specific neutralizing antibodies blocking the activity of TNF-α and IL-10 significantly improved the prognosis of sepsis, neutralizing antibodies to TNF-α in clinical trials did not yield satisfactory results." (PMID 38313013, 2024). "The underlying mechanism of this toxicity is unclear, and some studies suggested that an inflammation pathway including the IL‐6, iNOS, TNF‐α, and CD64 was involved, and a set of genes and proteins were found to play a role in neutrophil granulopoiesis in sepsis." (PMID 39305165, 2024). "Systemic TNF levels in CLP-treated and sham rats increased as early as 3 h after sepsis induction." (PMID 37542608, 2023). "Thus, there seems to be three different intracellular signaling events/pathways (i.e., TLR, TNFα, and PI3Kγ) that contribute to the internalization and thereby the reduction of CXCR2 cell surface expression in neutrophils in sepsis." (PMID 37048076, 2023). "The genes co-regulated by Acu-exo and sepsis were derived from multiple organs and systems, their interacting genes(HSP90AA1, GRB2, EGFR etc.)and signaling pathways(MAPK, TNF, JAK-STAT etc.)were involved in inflammation, immune regulation, metabolism, and cell proliferation and apoptosis." (PMID 37635258, 2023). "Thirdly, C-reactive protein measurement was not available in the bacterial sepsis group, nor was measurement of cytokines such as IL-1, IL-6 or TNF-α as these biomarkers are extensively studied in sepsis, regardless of etiology." (PMID 36982221, 2023). "The levels of TNF-α and IL-6 were significantly increased in MRAB 0227-treated sepsis mice." (PMID 37942076, 2023). "The binding of LPS or TNF-α to their respective receptors triggers the activation of Toll-like receptor 4 (TLR4), MAPK and nuclear factor kappa B (NF-κB) signaling pathways, leading to the release of cytokines, which plays a crucial role in sepsis development." (PMID 37869005, 2023). "Some studies have shown that the levels of characteristic cytokines such as TNF‐α, IL‐6, IL‐1β, IL‐1α, IL‐12, IL‐17, CXCL1, CXCL2, MCP‐1, IL‐8, CXCL10, GM‐CSF, M‐CSF, and G‐CSF in patients with septicemia are significantly higher than those in normal volunteers." (PMID 36684101, 2023). "In view of the arguments and evidence presented here, it is suggested that a combination of corticosteroids and/or anti-IL-6 and anti-TNF-α antibodies and GLA, DHLA, AA, EPA, DHA, along with vitamins C, B1, B6, B12, and folic acid, can prevent and suppress sepsis and other inflammatory conditions." (PMID 37759732, 2023).